BCL2 (BCL2 apoptosis regulator)
Diseases named in the same sentence as BCL2 in open-access papers (continued):
Sharing a sentence is not in itself a finding about the gene and the disease.
cancer (continued). "This study identified BAG3 as a potential target for combined cancer therapies with Bcl2-antagonists." (PMID 32121220, 2020). "Accordingly, pharmacologic inhibitors targeting pro-survival BCL-2 proteins have been developed to induce apoptosis in cancer cells." (PMID 32913197, 2020). "Significantly, over-expression of both XIAP and Bcl-2 contributes to tumorigenesis and have become major targets for developing anti-cancer therapeutics." (PMID 32587235, 2020). "In some cancer types, the anti-apoptotic protein Bcl2 plays a significant part in the formation of cancer progression." (PMID 33400732, 2020). "Bcl-2 is a widely investigated anti-apoptotic protein, is highly expressed in many cancers, and is a key player in drug resistance, suggesting its potential as a target for reversing drug resistance." (PMID 32974385, 2020). "The degree of BDA-366-induced cell death positively correlated with Bcl-2-protein levels, whereby cancer cells expressing the highest level of Bcl-2 displayed the highest sensitivity to BDA-366." (PMID 32943617, 2020). "Results of ongoing trials indicate that inhibitors of BCL2 alone or in combination with other drug/s can be an important tool in cancer therapy." (PMID 32938954, 2020). "Nuclear factor NF-κB plays an important role in countering the induction of apoptosis by regulating the transcription of apoptotic-related genes, such as Bcl-2, thus modulating the survival and growth of various cancers, including CCA." (PMID 32784671, 2020). "In this view, intense studies have been performed in order to identify Bcl-2 inhibitors to be used for cancer therapy, and cell death discoveries have been translated into the identification of novel therapies using Bcl-2 family inhibitors." (PMID 32455818, 2020). "We demonstrate that CAPE-MotAb cause a stronger dose-dependent growth arrest/apoptosis of cancer cells through the downregulation of Cyclin D1-CDK4, phospho-Rb, PARP-1, and anti-apoptotic protein Bcl2." (PMID 32825706, 2020). "Many studies show that an imbalance between Bax and Bcl-2, with increased levels of Bax and decreased levels of Bcl-2, affects lymphocytes proliferation and survival (such as Th, B, and NK cells) in patients with cancer." (PMID 32901694, 2020). "Taken together, compounds with potent activity for eliminating Bcl-2 or Mcl-1 in cancer cells are of great interest as good candidates for targeted therapy." (PMID 32260280, 2020). "An antiapoptotic role played by p16 has been shown to be associated with downregulation of proapoptotic proteins such as Bax‐Bak and cell cycle regulator Bcl‐2, and sensitization of proliferating cancer cells to cisplatin activity." (PMID 32945604, 2020). "Conversely, BCL2, BCL2L2, and MCL1 show downregulation across 2‐3 different cancer types, despite distal BCL2 regulation." (PMID 32419250, 2020). "The Bcl-2 protein is liked in several cancers and drug resistance to therapy is also known in this context." (PMID 32884211, 2020). "Given the over-expression of PRSS1 in the constructed cancer cell lines, we examined the expression alterations in Bcl-2 and Bax at the mRNA and protein levels." (PMID 33585454, 2020). "For example, the anti-apoptotic member BCL-2 is overexpressed in 90% of follicular B-cell lymphomas while the proapoptotic member PUMA is deleted in a range of cancers." (PMID 31636382, 2020). "Another antibody against epidermal growth factor, cetuximab, can regulate autophagic cell death in cancer cells by disrupting the interaction between Bcl-2 and Beclin-1." (PMID 33228222, 2020). "ROS can stimulate gene expression of B-cell lymphoma-2 (Bcl-2) via activation of NF-κB and therefore, EGCG’s scavenging activity of ROS is expected to downregulate the anti-apoptotic protein Bcl-2, leading to apoptotic cell death of cancer cells." (PMID 33027981, 2020). "Inhibition of antiapoptotic protein BCL-2 that is overexpressed in cancer cells is one of the most studied approaches in cancer research." (PMID 32328476, 2020).
cancer (continued). "On the one hand, the overexpression of BCL2 family members (MCL1 in type I B cells and BCL2 L12 in type III B cells) inhibits perforin and decreases the damage caused by cancer cells." (PMID 32944402, 2020). "Bcl-2 protects cancer cells against CTL-mediated cytotoxicity and is under the regulation of several oncogenic pathways, including the MAPK pathway." (PMID 35310881, 2020). "The level of Bcl-2 (antiapoptotic) and Bax (proapoptotic) expression in cancer cells was determined following treatment with the hexane extract of S. costus." (PMID 32766303, 2020). "Many clinical trials support the occurrence of an over-expression of the pro-survival Bcl-2 protein, including a down-regulation of the pro-apoptotic Bax, as negative prognostic marker in patients with breast and other cancers." (PMID 32517101, 2020). "Intriguingly, accumulated evidences have revealed that the sensitivity to cisplatin is conferred by suppression of Bcl-2 expression in various types of human cancers 34-37." (PMID 32047564, 2020). "While ABT-199 has been already approved for clinical usage, several other Bcl-2 inhibitors are currently in clinical trials as potential agents for cancer chemotherapy, including ABT-263 and S63845." (PMID 33207781, 2020). "Studies have reported that mitochondrial respiration is upregulated in cancer cells with RB1 deficiency, HRAS mutations, and BCL-2 overexpression." (PMID 33235318, 2020). "After treatment with BA, the expression of Bax was upregulated, whereas that of Bcl-2 was downregulated, suggested that BA-induced apoptosis might be associated with the mitochondrial apoptotic pathway, which is particularly relevant to cancer and the typical apoptotic signaling pathway." (PMID 32625089, 2020). "In many cancers the high level of Bcl-2 expression inhibits IP3R-mediated Ca2+ elevation, thus preventing apoptosis." (PMID 32455818, 2020). "Drug-resistant cancer cells in these hematologic neoplasms are induced by overexpression of the antiapoptotic B-cell lymphoma 2 (Bcl-2) protein families, such as Bcl-XL, Bcl-2, and Mcl-1." (PMID 33312200, 2020). "Activation of AKT allows Bcl-2 to outcompete Bax, resulting in an anti-apoptotic response and upregulation of Bcl-2 has been shown to be an important mechanism of chemo-resistance in cancer cells." (PMID 32411595, 2020). "In other types of cancers, and based on the treatment used, Bcl-2 acts downstream of Cer, preventing Cer -mediated death in Molt-4 cells without interfering with its vincristine-induced accumulation." (PMID 33048123, 2020). "For SAR study, five analogues of RT were synthesized and tested for their anti-cancer and Mcl-1- and Bcl-2-targeting effects." (PMID 32260280, 2020). "In summary, our data support the concept that BH3-mimetics are remarkable compounds to combine with cancer therapy when the BCL-2 network is altered." (PMID 32024199, 2020). "Several studies have shown that Zerumbone prevents the growth of the specific cancer cells through apoptosis induction by upregulating the Bax/Bcl-2 ratio." (PMID 32454937, 2020). "The recognition of the BCL-2 protein superfamily in regulating intrinsic apoptosis has brought attention to its targeting in overcoming treatment-related resistance in cancer therapy." (PMID 32131385, 2020). "In both models, reduction of XIAP and Bcl-2 levels in cancer cells “addicted” to high levels of these proteins initiate apoptosis." (PMID 32587235, 2020). "miRNA-21 inhibits phosphatase and tensin homolog (PTEN), thereby inhibiting the PI3K/AKT pathway and leading to increased proliferation, cancer cell survival, and Bcl-2 expression." (PMID 32076440, 2020).
cancer (continued). "Bcl-2, Bcl-xL and Mcl-1 are anti-apoptotic members of the Bcl-2 family and frequently dysregulated in various cancers." (PMID 32872659, 2020). "Since SAHA was reported to induce apoptosis to kill the cancer cells, the NEAT1/miR-129 mediated abnormal expression of Bcl-2 served as the major cause." (PMID 32692721, 2020). "We examined the expression of Bax, Bcl-2, and Caspase-3 after treating the cancer cells with hexane extract of S. costus because the hexane extract of S. costus showed the best IC50 for all the cell lines tested." (PMID 32766303, 2020). "In contrast, Bcl-2β is a splice variant of Bcl-2α (i.e., the wild-type Bcl-2), and overexpression of this Bcl-2 isoform has been shown to inhibit apoptosis and to increase chemoresistance/UV resistance in cancer cells." (PMID 32695778, 2020). "In collaboration with WT1/Early Growth Response 1 (EGR1), Bcl2 contributes to dysregulation of calcium homeostasis and signaling in cancer cells." (PMID 32856872, 2020). "Cancer cells often upregulate anti-apoptotic BCL-2 proteins, thus tilting the ratio of anti- versus pro-apoptotic members to fall in favor of apoptosis evasion, even in the presence of stimuli from chemotherapeutic agents." (PMID 32131385, 2020). "As MCL1 promotes drug resistance and overall survival, we propose that NOXA induction is an alternative therapeutic strategy to target MCL1 and either kill cancer cells that are dependent on MCL1 or sensitize cancer cells to other BCL2 inhibitors." (PMID 32824203, 2020). "Navitoclax, TW-37, GX15-070, and BM-1197 are Bcl-2 or Bcl-xL inhibitors with anti-cancer activity in a broad range of cancer types." (PMID 33114695, 2020). "Among the anti-apoptotic proteins, Bcl-2 protein plays a pivotal role in cell survival activities as well as chemo-resistance which frequently dysregulated in many types of cancers, including PCa." (PMID 32131560, 2020). "We and others have shown that NOXA-inducing compounds can sensitize cancer cells to other compounds, such as inhibitors of BCL2 and BCL-XL." (PMID 32824203, 2020). "The recent development of Bcl-2 inhibitors has offered a novel therapeutic approach to treating cancer." (PMID 32367199, 2020). "The molecular mechanisms are mainly through targeting some apoptotic pathways in cancer, for example, Bcl-2/Bax, caspases, PI3K/Akt, JAK2/STAT3, MAPK, and AMPK." (PMID 32774302, 2020). "It has been reported that PL induces apoptosis of various cancer cells by downregulating Bcl-2 in a dose-dependent manner." (PMID 31948057, 2020). "We used the CRISPR‐Cas9 system to interfere with Bcl‐2/Bax in cancer cells to promote cell apoptosis." (PMID 33135339, 2020). "Positive correlation with cancer-promoting genes BCL2, BCLxL, HIF1A, VEGFA, ACTA2, CCL2, PTGS2, and CDKN1A, but not Ki67, was demonstrated, particularly for ILs’ receptors." (PMID 32512917, 2020). "Apoptosis evasion by dysregulation of anti-apoptotic BCL-2 members (BCL-2, MCL-1, BCL-XL) is a common hallmark in cancers." (PMID 32183335, 2020). "The BCL-2 anti-apoptotic proteins are over-expressed in many cancers and hence are attractive therapeutic targets." (PMID 33214852, 2020). "Other compounds such as Gossypol, Navitoclax, ABT-737 and α-TOS act as mimetics of the Bcl-2 homology-3 domain to kill cancer cells via activation of post-mitochondrial apoptotic signalling." (PMID 33114695, 2020). "In the syngeneic mouse model, we evidenced the ability of cancer-specific bcl-2 to impair T cell response, through reduced production of IFNγ and the effector memory T cells population." (PMID 32269145, 2020).
cancer (continued). "Overexpression of SPHK2 was reported to suppress cell growth and induce apoptosis by sequestration of BCL2 by its BH3 domain, while siRNA-mediated loss of SPHK2 from cancer cells produced a strong anti-cancer effects." (PMID 32260399, 2020). "Small molecule apoptosis sensitisers, such as BCL-2 antagonists restore or induce cell death signalling in cancer cells." (PMID 33066609, 2020). "Studies that used nobiletin on human cancer cell lines (gastric, hepatic, and breast) shown that nobiletin induced apoptotic cell death by reducing the expression of BCL2." (PMID 32727154, 2020). "Bcl-2 is a potential chemotherapeutic target for certain cancers, typically those involving Bcl-2 overexpression." (PMID 33046037, 2020). "Accumulating evidence has indicated that co-delivery of Bcl-2-targeted siRNA and chemotherapeutics by NPs is an alternative to overcoming drug resistance in cancer." (PMID 32974385, 2020). "Preclinical evidence also supports the Bcl-2 G-quadruplex (G4)-selective approach to treat cancer and to circumvent the limitations of Bcl-2 protein-based therapeutics." (PMID 32455818, 2020). "In either model, reduction of both XIAP and Bcl-2 in cancer cells “addicted” to high levels of these proteins stimulates apoptosis." (PMID 32587235, 2020). "The combination of glaucarubin-induced DNA damage and treatment with the FDA-approved BCL-2 inhibitor ABT-199 completely inhibits the proliferation of this subpopulation of cancer cells." (PMID 32093022, 2020). "Knowing the BCL-2 profile induced by a drug helps design a strategy based on BH3-mimetics predicted to be successful for a specific cancer." (PMID 32024199, 2020). "The best example of the key role of non-coding RNAs in the development of new drugs for cancer treatment is the use of venetoclax in patients with high BCL-2 protein levels, correlated with deletions on chromosome 13 and loss of miR-15a and miR-16-1." (PMID 32937758, 2020). "Because of the central role of BCL-2 proteins in preserving cancer cell viability, intense effort has centred upon developing drugs that neutralize anti-apoptotic Bcl-2 function." (PMID 32792521, 2020). "Bax and Bcl-2 apoptotic genes have been of tremendous interest to clinicians who study cancer therapy." (PMID 33330009, 2020). "Several chemical inhibitors have been developed to bind anti-apoptotic of Bcl-2 proteins and induce cancer cell death including Bcl-PROTACs." (PMID 32630560, 2020). "In recent years, the anti-apoptotic protein BCL-2 has emerged as an attractive therapeutic target in a variety of cancers, including AML." (PMID 32992732, 2020). "Myeloid cell leukemia 1 (Mcl-1) and B-cell lymphoma 2 (Bcl-2) proteins are promising targets for cancer therapy." (PMID 32260280, 2020). "Bcl-2 is an important target for cancer therapy since it is highly expressed in a wide range of cancers, which renders them resistant to apoptotic stimuli and chemotherapeutic agents." (PMID 32587235, 2020). "All these natural extracts significantly increased the expression of Bax protein and also decreased the level of Bcl-2 protein in individual cancer cells." (PMID 32977472, 2020). "Bcl-2 and Bcl-XL proteins are known to be overexpressed in various human cancers and act as suppressors of apoptosis, resulting in the survival of malignant cells." (PMID 32774424, 2020). "Bcl-2 is a proto-oncogene that inhibits apoptosis and promotes survival of cancer cells under deleterious condition." (PMID 32687064, 2020).
cancer (continued). "Altering the balance between anti-apoptotic and pro-apoptotic BCL-2 proteins can lead to disruption of the apoptotic process and the aberrant survival of cancer cells." (PMID 32290241, 2020). "APG-1252, a novel Bcl-2/Bcl-XL inhibitor, was considered for the treatment of cancers including small cell lung cancer (SCLC) as investigational new drug by the FDA (NCT03387332)." (PMID 32101536, 2020). "Taken together, our data suggest that DC matured by the four-cytokine cocktail combined with exogenous Bcl-2 and IL-12p70 gene expression represents a promising approach for clinical applications in cancer immunotherapy." (PMID 32292785, 2020). "Single agent antitumor activity of S1, the BH3-mimetic dual inhibitor of Bcl-2 and Mcl-1, and its derivative B4, has been also reported in cancer models with different origin." (PMID 32455818, 2020). "Compound 4j, containing a 4-trifluoromethylphenyl group directly attached to the oxadiazole ring, possessed the most potent anticancer activity across the Bcl-2 expressing human cancer cell lines (MDA-MB-231, HeLa, KG1a; sub-micromolar IC50 values)." (PMID 33256166, 2020). "Fadraciclib preclinical pharmacology data support its therapeutic potential in CDK9- or CDK2-dependent cancers and as a rational combination with BCL2 inhibitors in hematological malignancies." (PMID 32645016, 2020). "The resistance of cancer cells to apoptosis mediated by Bcl‐2 is a distinguishing feature of cancer; inhibition of Bcl‐2 antiapoptotic proteins will be a new way to enhance the effectiveness of chemotherapy." (PMID 32346976, 2020). "Selenium was shown to induce downregulation of Bcl-2 and Ki-67 expressions in many cancer cell lines." (PMID 32872195, 2020). "It is widely accepted that Bcl-2 protein-mediated apoptosis blockade contributes to malignant transformation in multiple human cancers." (PMID 32047564, 2020). "The anti-apoptotic BCL-2 proteins are overexpressed in many cancers and thus have become attractive therapeutic targets especially with the development of BH3-mimetics such as ABT-263 which selectively targets these proteins." (PMID 33214852, 2020). "Significantly, compound shows more potent anticancer activity in vivo, by removing the cancer burden via apoptosis along with increased Bax and caspase 3 and decreased Bcl2 expression." (PMID 32962014, 2020). "For example, overexpression of MCL1 induces resistance to many widely used anti-cancer therapies drugs such as BCL2 inhibitors, such as paclitaxel, vincristine, and gemcitabine." (PMID 33126914, 2020). "Bcl-2 has been proven to be an anti-apoptotic protein and is overexpressed in multiple malignant tumors." (PMID 32528278, 2020). "Since the discovery of Bcl-2, the founding member of the family, many papers have been published regarding the role that Bcl-2 anti-apoptotic members play in cancer and in drug resistance, as well as on their use for cancer therapy." (PMID 32455818, 2020). "The overexpression of Bcl2 and BclxL are known to block apoptosis and promote cancer cell proliferation, thus making them as attractive targets for cancer drug discovery." (PMID 32703189, 2020). "These NPs were loaded with DOX as an antineoplastic agent, and Bcl-2-targeting siRNA to induce apoptosis in cancer cells." (PMID 32532030, 2020). "Some organometallic complexes have been found to be more selective to Bcl-2 than to telomeric quadruplex, to have poor affinity for duplex DNA and to exhibit in vitro and in vivo antitumoral activity against cancer models from different histotypes." (PMID 32455818, 2020).